RN7SKP77 (RN7SK pseudogene 77)
Gene: Miscellaneous RNA gene on chromosome 9 (106,679,977 to 106,680,329, forward strand). Ensembl gene ENSG00000200131.
Homologues: Orthologues: chimpanzee 7SK (87% identical). Paralogues in human: RN7SKP240 (69% identical), 7SK (68% identical), RN7SKP71 (68% identical), RN7SKP124 (67% identical), RN7SKP127 (67% identical), RN7SKP79 (67% identical), RN7SKP30 (66% identical), RN7SKP86 (66% identical), RN7SKP174 (66% identical), RN7SKP173 (65% identical), RN7SKP176 (65% identical), RN7SKP180 (65% identical), and 284 more.